FAM20B (FAM20B glycosaminoglycan xylosylkinase)
Description:
Responsible for the 2-O-phosphorylation of xylose in the glycosaminoglycan-protein linkage region of proteoglycans thereby regulating the amount of mature GAG chains. Sulfated glycosaminoglycans (GAGs), including heparan sulfate and chondroitin sulfate, are synthesized on the so-called common GAG-protein linkage region (GlcUAbeta1-3Galbeta1-3Galbeta1-4Xylbeta1-O-Ser) of core proteins, which is formed by the stepwise addition of monosaccharide residues by the respective specific glycosyltransferases. Xylose 2-O-phosphorylation may influence the catalytic activity of B3GAT3 (GlcAT-I) which completes the precursor tetrasaccharide of GAG-protein linkage regions on which the repeating disaccharide region is synthesized.
Synonyms: KIAA0475; GXK1
Tractability: Antibody: UniProt predicts a signal peptide or a membrane-spanning region. PROTAC: ubiquitination databases record sites on it; its protein half-life has been measured.
Gene: Protein-coding gene on chromosome 1 (179,025,804 to 179,076,567, forward strand). Ensembl gene ENSG00000116199.
Subcellular location: Golgi apparatus membrane
Subcellular location (Human Protein Atlas): Golgi apparatus; Nucleoplasm
Pathways (Reactome):
Metabolism: Glycosaminoglycan-protein linkage region biosynthesis
Gene Ontology:
Molecular function: phosphotransferase activity, alcohol group as acceptor; protein binding
Biological process: negative regulation of proteoglycan biosynthetic process; proteoglycan biosynthetic process
Cellular component: Golgi apparatus; Golgi membrane; cytoplasm
Genetic constraint (gnomAD): Loss-of-function variants: 16 observed, 32.31 expected, observed/expected ratio (o/e) 0.5, 90% interval 0.33 to 0.75. The upper end of that interval is the gene's LOEUF score, 0.75, which puts it in group 3 of 6, group 1 being the genes least tolerant of losing a copy. Missense variants: 349 observed, 424.51 expected, observed/expected ratio (o/e) 0.82, 90% interval 0.75 to 0.9. Synonymous variants: 144 observed, 159.09 expected, observed/expected ratio (o/e) 0.91, 90% interval 0.79 to 1.04.
Gene-disease validity (ClinGen):
ClinGen rates the evidence that FAM20B causes each of these diseases.
congenital disorder of glycosylation (autosomal recessive): Limited. Congenital disorder of glycosylation (CDG) is a fast growing group of inborn errors of metabolism characterized by defective activity of enzymes that participate in glycosylation (modification of proteins and other macromolecules by adding and processing of oligosaccharide side chains).
Homologues: Orthologues: chimpanzee FAM20B (99% identical), guinea pig FAM20B (99% identical), macaque FAM20B (99% identical), dog FAM20B (98% identical), pig FAM20B (98% identical), rabbit FAM20B (98% identical), mouse Fam20b (97% identical), rat Fam20b (97% identical), tropical clawed frog fam20b (81% identical), zebrafish fam20b (77% identical), Drosophila melanogaster CG3631 (37% identical). Paralogues in human: FAM20C (39% identical), FAM20A (36% identical).
Diseases named in the same sentence as FAM20B in open-access papers:
FAM20B is named in the same sentence as 22 diseases in open-access papers, as found by Europe PMC text mining. Sharing a sentence is not in itself a finding about the gene and the disease. The quoted sentences say what the papers report.
chondrosarcoma (3 papers, 2016 to 2025). A malignant cartilaginous matrix-producing mesenchymal neoplasm arising from the bone and soft tissue. "In contrast to the chondrosarcoma in the mesoderm-derived knee cartilage, a hypoplastic condylar cartilage was previously reported when Fam20b was inactivated in mouse CNCCs, implying an opposite role of Fam20b in the CNCC-related chondrogenesis and osteogenesis." (PMID 40362273, 2025).
Raine syndrome (3 papers, 2011 to 2022). "In closing, we discuss the phenotype of fam20b mutant zebrafish with respect to excessive bone formation in Raine syndrome patients, who contain mutations in the paralogous gene FAM20C." (PMID 21901110, 2011). "As such, fam20b mutants may provide a completely new etiology for Raine syndrome: defects in chondrocyte differentiation underlie the increased perichondral bone (i.e., osteosclerosis) and skeletal dysmorphies observed in these humans." (PMID 21901110, 2011). "In particular, we note that humans with Raine syndrome display similar facial dysmorphies and osteosclerosis as seen in fam20b mutant zebrafish, potentiating these fish as an informative model by which to understand the etiology of Raine syndrome." (PMID 21901110, 2011).
psoriasis (2 papers, 2021 to 2022). An autoimmune condition characterized by red, well-delineated plaques with silvery scales that are usually on the extensor surfaces and scalp. "FAM20B, a psoriasis-risk gene, regulates the sulfation profile of CS chains and total amount of GAG synthesized in cells." (PMID 33495490, 2021). "Based on these findings, we hypothesized that a decrease in the expression of FAM20B would impact CS biosynthesis and would be associated with psoriasis." (PMID 33495490, 2021).
Alzheimer disease (1 paper, 2024). A progressive, neurodegenerative disease characterized by loss of function and death of nerve cells in several areas of the brain leading to loss of cognitive function such as memory and language. "Though the literature on this is gene is very limited, a SNP in FAM20B (rs4652345) was the 16th most strongly associated locus in a GWAS of individuals with polygenic risk extremes for Alzheimer's disease in the UK Biobank." (PMID 38431614, 2024).
atherosclerosis (1 paper, 2025). A disease characterized by the build-up of fatty material and calcium deposition in the arterial wall resulting in partial or complete occlusion of the arterial lumen. "Therefore, studying the regulation of the expression of FAM20B and XYLP genes in normal and pathological conditions may help to understand the defects in the synthesis of GAG chains associated with several diseases such as cancer, atherosclerosis, and osteoarthritis." (PMID 40422215, 2025).
bone osteosarcoma (1 paper, 2025). A usually aggressive malignant bone-forming mesenchymal neoplasm arising from the bone. "On the other hand, in agreement with our study, it was shown that the knockout of FAM20B in bone osteosarcoma cells, U2OS, led to reduction in the synthesis of GAGs." (PMID 40422215, 2025).
dystroglycanopathy (1 paper, 2025). "FAM20B was identified in a dystroglycanopathy screen, however, its role in matriglycan formation was unknown." (PMID 41279211, 2025).
glioblastoma (1 paper, 2025). The most malignant astrocytic tumor (WHO grade IV). "Expression of FAM20B in glioblastoma cells led to a significant reduction in proliferation and in the ability of cells to migrate in scratch-wound healing assays." (PMID 40422215, 2025). "Glioblastoma cells transfected with FAM20B presented a reduction in cell proliferation of about 14% at 24 h and 28% at 48 h, compared to control." (PMID 40422215, 2025). "Indeed, expression of FAM20B in glioblastoma cells reduced the number of cells that migrate in the scratch area by about 36% at 6 h and 53% at 24 h, compared to control." (PMID 40422215, 2025). "Finally, we found that FAM20B inhibited proliferation and migration of glioblastoma cells, thus revealing the critical role of GAG chains of PGs in glioblastoma cell tumorigenesis." (PMID 40422215, 2025). "Our findings on FAM20B inhibitory effects on proliferation and migration of glioblastoma cells provide evidence that GAG chains play a critical role in glioblastoma tumorigenesis and could lead to the development of new strategies against glioblastoma tumorigenesis." (PMID 40422215, 2025). "Therefore, FAM20B-dependent inhibition of PG–GAG synthesis could contribute to the cell proliferation and migration defects observed in glioblastoma cells." (PMID 40422215, 2025).
intervertebral disc disorder (1 paper, 2023). "Inactivation of Fam20b in the oral epithelium led to supernumerary incisors and compromised enamel, while deletion of Fam20b by Col1-cre led to severe spine deformity and intervertebral disc disorder via the altered P38, ERK, and JNK signaling pathways." (PMID 37298583, 2023).
lung carcinoma (1 paper, 2025). "We next analyzed the effect of FAM20B mutations on the synthesis of decorin in human lung cancer cell line A549, which abundantly produced this PG in the medium." (PMID 40422215, 2025).
metastatic tumors (1 paper, 2015). "Second, the transcription of FAM20B, which encodes xylose kinase 1 that catalyzes a transient phosphorilation of the Xyl residue involved in the control of GAG biosynthesis, also decreased significantly, though only in non-metastatic tumors." (PMID 26482785, 2015).
tumor (1 paper, 2024). "The peptides with increased presentation in SK-Mel-28 dr cells derived from EIF4B, FAM20B, LDHB, CYCS, C5orf22, RCAN1 and DIEXF and were recurrently identified in TvHdb in a variety of tumor patients." (PMID 39835134, 2024).
FAM20B also shares sentences with these, for which no sentence is quoted: cancer (2 papers); Cleidocranial dysplasia (1); Desbuquois dysplasia (1); genetic disease (1); Insulin resistance (1); Obesity (1); osteoarthritis (1); osteosclerosis (1); polycystic kidney disease (1); schizophrenia (1).